SS18 (SS18 subunit of BAF chromatin remodeling complex)
Description:
Appears to function synergistically with RBM14 as a transcriptional coactivator. Isoform 1 and isoform 2 function in nuclear receptor coactivation. Isoform 1 and isoform 2 function in general transcriptional coactivation. Component of SWI/SNF chromatin remodeling subcomplex GBAF that carries out key enzymatic activities, changing chromatin structure by altering DNA-histone contacts within a nucleosome in an ATP-dependent manner.
Synonyms: SSXT; SYT; SMARCL1
Tractability: PROTAC: ubiquitination databases record sites on it.
Gene: Protein-coding gene on chromosome 18 (26,016,253 to 26,091,217, reverse strand). Ensembl gene ENSG00000141380.
Subcellular location: Nucleus
Subcellular location (Human Protein Atlas): Nucleoplasm; Cytosol
Pathways (Reactome):
Chromatin organization: Formation of neuronal progenitor and neuronal BAF (npBAF and nBAF); Formation of the canonical BAF (cBAF) complex; Formation of the embryonic stem cell BAF (esBAF) complex; Formation of the non-canonical BAF (ncBAF) complex
Developmental Biology: Regulation of MITF-M-dependent genes involved in pigmentation
Gene expression (Transcription): Regulation of endogenous retroelements by Piwi-interacting RNAs (piRNAs)
Gene Ontology:
Molecular function: protein binding; transcription coactivator activity
Biological process: positive regulation of transcription by RNA polymerase II; chromatin remodeling; negative regulation of cell differentiation; positive regulation of cell population proliferation; positive regulation of stem cell population maintenance; regulation of transcription by RNA polymerase II
Cellular component: SWI/SNF complex; chromatin; GBAF complex; nucleoplasm; nucleus
Genetic constraint (gnomAD): Loss-of-function variants: 18 observed, 56.37 expected, observed/expected ratio (o/e) 0.32, 90% interval 0.22 to 0.47. The upper end of that interval is the gene's LOEUF score, 0.47, which puts it in group 2 of 6, group 1 being the genes least tolerant of losing a copy. Missense variants: 454 observed, 461.3 expected, observed/expected ratio (o/e) 0.98, 90% interval 0.91 to 1.06. Synonymous variants: 149 observed, 143.1 expected, observed/expected ratio (o/e) 1.04, 90% interval 0.91 to 1.19.
Homologues: Orthologues: chimpanzee SS18 (99% identical), macaque SS18 (99% identical), pig SS18 (99% identical), dog SS18 (99% identical), rabbit SS18 (99% identical), guinea pig SS18 (97% identical), mouse Ss18 (96% identical), rat Ss18 (95% identical), tropical clawed frog ss18 (89% identical), zebrafish ss18 (69% identical), Caenorhabditis elegans ZK973.9 (21% identical). Paralogues in human: SS18L1 (59% identical), SS18L2 (9% identical).
Diseases named in the same sentence as SS18 in open-access papers:
SS18 is named in the same sentence as 54 diseases in open-access papers, as found by Europe PMC text mining. Sharing a sentence is not in itself a finding about the gene and the disease. The quoted sentences say what the papers report.
synovial sarcoma (211 papers, 2010 to 2026). "To confirm the diagnosis, we performed a translocation study, which identified the SS18 gene translocation at 18q11, a hallmark of synovial sarcoma." (PMID 41635361, 2026). "Synovial sarcoma is a translocation-associated soft-tissue sarcoma defined by the SS18-SSX fusion gene and typically exhibits biphasic or monophasic histology with at least focal epithelial marker expression." (PMID 42294281, 2026). "Since synovial sarcoma exhibits genomic stability with few somatic mutations aside from the SS18-SSX translocation, the fusion oncoprotein SS18-SSX is considered the key oncogenic driver, disrupting differentiation through widespread epigenetic dysregulation." (PMID 41149817, 2025). "We now know that SS18-SSX also has a “self-protective” function that is not involved in synovial sarcomagenesis, but instead sustains synovial sarcoma cell survival upon loss of SS18-SSX." (PMID 40296913, 2025). "The expression of transcriptional repressor GATA binding 1 (TRPS1) is frequent in synovial sarcoma, which is linked to the activity of the SS18-SSX fusion oncoprotein." (PMID 39451213, 2024). "Synovial sarcoma is associated with the translocation of t(X; 18)(p11; q11), resulting in SS18-SSX fusion genes." (PMID 39015801, 2024). "Genomic lesions targeting SS18, synovial sarcoma translocation chromosome 18, are associated with a variety of soft tissue tumors as well as a subset of CRC48." (PMID 38654044, 2024). "Various histological subtypes of STS have been associated with specific genetic fusions, such as SS18::SSX in synovial sarcoma, FUS::DDIT3 in myxoid liposarcoma, and TMP4::ALK in inflammatory myofibroblastic tumor." (PMID 36980578, 2023). "Synovial sarcoma (SyS) is a rare malignant soft tissue sarcoma bearing the chromosomal translocation t(X;18), which encodes the fusion oncoprotein SS18::SSX." (PMID 37568703, 2023). "Using a break-apart FISH probe, a break in the SS18 gene, a genetic alteration diagnostic for synovial sarcoma, in this case classified as monophasic synovial sarcoma, was demonstrated in the tumor." (PMID 36765281, 2023). "Our study addresses the molecular mechanism underlying SS18-SSX chromatin recruitment in synovial sarcoma." (PMID 37735617, 2023). "Changes in canonical BAF (cBAF) complexes driven by the SS18-SSX oncoprotein causes synovial sarcoma gene expression." (PMID 36969064, 2023). "SS18L2 is the homolog of the SS18 gene, which is associated with chromosomal translocation characteristics of synovial sarcoma." (PMID 35973998, 2022). "In parallel, synovial sarcoma is defined by the hallmark SS18–SSX fusion oncoprotein, which leads to a rare gain-of-function by mistargeting BAF and activates bivalent genes located at broad polycomb domains." (PMID 34070411, 2021). "Here we identify a minimal region of the human SS18-SSX fusion oncoprotein (the hallmark driver of synovial sarcoma) that mediates a direct interaction between the mSWI/SNF complex and the nucleosome acidic patch." (PMID 32747783, 2020). "SS18 derives its name from a chromosomal translocation event that is frequently associated with tumorigenesis in synovial sarcoma." (PMID 33143733, 2020). "The best studied examples of how mutations of chromatin remodellers can cause malignancies are BAF47 (= SmarcB1) loss in rhabdoid tumours and the SS18-SSX fusion protein in synovial sarcoma." (PMID 30898143, 2019). "Over 95% of synovial sarcomas can be characterized by expression of the SS18-SSX gene and it is used as a routine diagnostic marker for this type of cancer." (PMID 30909651, 2019). "The presence of a chromosomal translocation-associated SS18-SSX-fusion gene is causally linked to development of primary synovial sarcoma." (PMID 30627328, 2018). "We show that BRD9 is part of SS18-SSX containing BAF complexes in synovial sarcoma cells; and that the association of BRD9 with the BAF complex is functionally essential." (PMID 30431433, 2018).
synovial sarcoma (continued). "We demonstrate that BRD9 supports oncogenic mechanisms underlying the SS18-SSX fusion in synovial sarcoma and highlight targeted degradation of BRD9 as a potential therapeutic opportunity in this disease." (PMID 30431433, 2018). "Here we report use of the proximity ligation assay to confirm the oncogenic association of SS18-SSX with its co-factor TLE1 in multiple human synovial sarcoma cell lines and in surgically-excised human tumor tissue." (PMID 27120803, 2016). "In summary, the fusion protein SS18-SSX in synovial sarcoma is believed to promote oncogenesis though either loss of negative regulation of EZH2/polycomb or by direct recruitment of EZH2/polycomb." (PMID 27125524, 2016). "SS18–SSX (formerly called SYT–SSX) fusion gene has been established clinicallyas a molecular diagnostic test for synovial sarcoma, but the prognostic value of the fusion gene variant for survival is controversial." (PMID 26217552, 2015). "SSX was initially identified as part of the SS18/SSX fusion gene in synovial sarcoma and as the melanoma associated tumor antigen HOM-Mel40." (PMID 24787708, 2014). "SS18 is a putative SWI/SNF subunit which has been implicated in the etiology of synovial sarcomas by virtue of being a target for oncogenic chromosomal translocations that underlie synovial sarcomas." (PMID 22442726, 2012). "The rationale for SB939 treatment in translocation-associated sarcomas is perhaps the best explained in the synovial sarcoma, where fusions of the SS18 and SSX (1, 2 and 4) genes are characteristic." (PMID 21285985, 2011). "Similarly, functional studies in synovial sarcoma cell lines have linked the expression of the SS18::SSX fusion transcript to levels of YAP/TAZ, which have been mechanistically linked to IGF-1R/PI3K/AKT signalling." (PMID 40983796, 2025). "The effectiveness of SUMO2 inhibition in synovial sarcoma models by specifically suppressing the pathogenic features of the SS18::SSX fusion oncoprotein indicate that SUMO2 is a highly selective vulnerability in synovial sarcoma as indicated by our analysis of the Dependency Maps (DepMap) data." (PMID 40804185, 2025). "We find that exposure of synovial sarcoma cells to FK228, a potent HDAC1/2 inhibitor, leads to the induction of FYN mRNA and protein expression which could render synovial sarcoma cells resistant to growth inhibition after loss of SS18-SSX function." (PMID 39045458, 2024). "A key step in the mechanism underlying synovial sarcoma is the fusion of SS18 and SSX genes." (PMID 39045458, 2024). "This raises the question of whether PRC1.1 inhibition alone is able to deplete the mark in synovial sarcoma cells, resulting in the loss of SS18-SSX at its target sites." (PMID 37735617, 2023). "Sarcoma diagnosis relies, not only on morphological and immunohistochemical features, but also on molecular alterations, such as EWS/FLI1 fusion in Ewing sarcoma (EWS), SS18-SSX fusion in synovial sarcoma, or kit mutation in gastrointestinal stromal tumors (GIST)." (PMID 36430703, 2022). "For example, MDM2 amplification is present in most dedifferentiated liposarcomas and typically co-amplified with CDK4 and/or HMGA2, synovial sarcomas (SS) are often characterized by SS18–SSX fusions, and presence of MYOD1 mutations indicate spindle cell/sclerosing rhabdomyosarcoma." (PMID 35053600, 2022). "The strongest association was found for LMC9 and synovial sarcoma (point biserial correlation coefficient (rpb) = 0.97) reflecting the dramatic changes to their methylome, which occur in this subtype as a consequence of an SS18-SSX gene fusion." (PMID 33980253, 2021). "Synovial sarcoma is a malignant mesenchymal neoplasm characterized by SS18-SSX gene fusions associated with t(X;18) chromosome translocation, characteristic biphasic morphologies consisting of both mesenchymal and epithelial components, highly invasive growth, and poor prognosis." (PMID 32019274, 2020).
synovial sarcoma (continued). "Additionally, the SS18-SSX translocation is frequently the sole chromosomal aberration observed in synovial sarcoma, and there are very few additional mutations present in this indication." (PMID 27391784, 2016). "Here we show that preclinical models of synovial sarcoma—a cancer characterized by functional SMARCB1 loss via its displacement from the SWI/SNF complex through the pathognomonic SS18-SSX fusion protein—display sensitivity to pharmacologic inhibition of EZH2, the catalytic subunit of PRC2." (PMID 27391784, 2016). "Although the SW982 cell line was formerly classified as synovial sarcoma, the molecular hallmark of synovial sarcoma is the SS18-SSX translocation, and therefore the SW982 cell line is likely to be mis-classified and represent a separate, distinct type of soft tissue sarcoma." (PMID 27391784, 2016). "Thus, CBP/p300 dual inhibitors could be promising for SMARCA4/SMARCA2-deficient lung cancer and SS18–SSX fusion synovial sarcoma, which are entirely deficient in the cBAF complex." (PMID 39625239, 2025). "The most common molecular alterations (excluding canonical SS18::SSX fusions in synovial sarcoma) involved ATM (18%), ARID1A (9%), CTNNB1 (9%), PALB2 (9%), and NF1 (9%), while 46% of profiled cases showed no detectable alterations." (PMID 41504936, 2026). "Molecular confirmation was obtained by searching for the SS18 gene translocation characteristic of synovial sarcoma using the Fluorescence in Situ Hybridization (FISH) technique, the result of which was positive." (PMID 41658667, 2026). "Synovial sarcoma harbours a pathognomonic t (X; 18) translocation resulting in either SS18::SSX1, SS18::SSX2 or SS18::SSX4 fusion genes." (PMID 40666501, 2025). "Synovial sarcoma constitutes 5–10% of all soft tissue sarcomas and is characterized by its unique pathognomonic chromosomal translocations between SS18 and SSX1/2, and less commonly SSX4." (PMID 40563544, 2025). "In light of these findings, SS18-SSX has been generally considered an appealing therapeutic target for synovial sarcoma treatment." (PMID 40296913, 2025). "The t(X;18)(p11.2;q11.2) translocation, which results in the SS18-SSX fusion gene and induces cancer development, is the hallmark feature of synovial sarcoma." (PMID 40718269, 2025). "Our assay reported several diagnostic fusions, including PAX3 and PAX7 joining with FOXO1 in alveolar rhabdomyosarcoma and SS18-SSX fusion in synovial sarcomas." (PMID 40711866, 2025). "This function of SS18-SSX was further validated across three synovial sarcoma cell lines, where it was demonstrated that both CREB S133 phosphorylation and the expression of CREB downstream targets were contingent upon the presence of SS18-SSX." (PMID 40584293, 2025). "SS18 break-apart FISH is more readily available as it is already widely used as an aid in the diagnosis of synovial sarcoma." (PMID 40176070, 2025). "An in-frame fusion of the SS18 subunit of the SWI/SNF chromatin remodeling complex with a member of the SSX family defines synovial sarcoma." (PMID 39625239, 2025). "Synovial sarcoma (SySa) is a malignant soft tissue tumor that is characterized by an SS18::SSX fusion protein, which integrates into BAF chromatin remodeling complexes and alters global gene transcription." (PMID 41440042, 2025). "Cyra et al64 elucidated the role of the SS18-SSX fusion protein in facilitating CREB (cyclic-AMP response element-binding) activation within synovial sarcoma." (PMID 40584293, 2025). "To differentiate it from synovial sarcoma, we performed SS18 gene testing on the patient, as the detection of SS18 gene translocation is considered the gold standard for diagnosing synovial sarcoma." (PMID 40826697, 2025).
synovial sarcoma (continued). "Synovial sarcoma is an aggressive soft-tissue cancer driven by the chimeric SS18::SSX fusion oncoprotein, which disrupts chromatin remodeling by combining two antagonistic transcriptional regulators." (PMID 40299558, 2025). "Concomitantly, genes activated by SS18::SSX in synovial sarcoma were repressed, including HOX genes HOXC6, HOXA10 as well as SRSF1 and TYMS." (PMID 40804185, 2025). "Synovial sarcoma is a rare and aggressive mesenchymal neoplasm characterised by the presence of the SS18-SSX fusion oncogene, resulting from the chromosomal translocation t(X;18)(p11.2;q11.2)." (PMID 41561516, 2025). "The incorporation of the SS18–SSX fusion oncoprotein into the SWI/SNF complex activates a synovial sarcoma transcriptional signature, thereby driving sarcomagenesis." (PMID 40563544, 2025). "The second most frequent type of mesenchymal tumor among the specimens tested in our laboratory was synovial sarcoma, characterized by the presence of the SS18 translocation." (PMID 40718211, 2025). "Although adamantinoma and synovial sarcoma of the tibia share morphologic and immunophenotypic similarities, SS18 translocation is a known marker of Synovial sarcoma." (PMID 40249565, 2025). "Knockdown of SS18-SSX moderately suppressed proliferation in two out of three synovial sarcoma organoids, with a more pronounced inhibitory effect observed in the spheroids." (PMID 41422105, 2025). "Targeted therapy that aims to block the oncogenic pathways driven by SS18-SSX in particular through disruption of its complex with transcription regulators is an active area of synovial sarcoma research." (PMID 40296913, 2025). "In synovial sarcoma cell lines harboring an SS18–SSX fusion, degradation of the BAF complex is promoted, although the stability of the ncBAF complex is not affected; this suggests that the function of the BAF complex is suppressed." (PMID 39625239, 2025). "The majority of synovial sarcomas (>90 %) carry the t(X; 18) chromosomal translocation, which results in the fusion of the SS18 gene (SYT) and the SSX gene." (PMID 40502213, 2025). "Many of these genes appear to be expressed in an SS18-SSX-dependent manner, in line with the traditional thinking that SS18-SSX establishes an oncogenic program driving synovial sarcoma development." (PMID 40296913, 2025). "Pathognomonic fusions were also identified, such as PAX3-FOXO1 and PAX7-FOXO1 in alveolar rhabdomyosarcoma, SS18-SSX in synovial sarcoma, and NAB2-STAT6 in solitary fibrous tumors." (PMID 40711866, 2025). "The SS18-SSX fusion gene is a specific and reliable diagnostic marker for synovial sarcoma due to its unique occurrence in this cancer type." (PMID 40296913, 2025). "The analysis of SS18-SSX fusion transcripts was conducted using RT-PCR on 27 tumors diagnosed as synovial sarcomas and confirmed by FISH." (PMID 41149817, 2025). "Synovial sarcoma is a high-grade soft tissue malignancy characterized by a unique fusion gene known as SS18-SSX." (PMID 40296913, 2025). "The SS18::SSX oncogene is the driver of synovial sarcoma, an aggressive cancer presenting in young adults that has poor long-term outcomes." (PMID 40849585, 2025). "Synovial sarcomas is a rare aggressive cancer characterized by aberrant SS18::SSX translocation and altered chromatin accessibility." (PMID 40804185, 2025). "As an example, Mivebresib was also reported to induce G1 arrest and exhibited dependency on SS18-SSX fusion expression in synovial sarcoma (SS)." (PMID 41166819, 2025). "The SS18 break-apart FISH assay is widely available and frequently utilized as an adjunct for the diagnostic evaluation of synovial sarcoma." (PMID 38982505, 2024). "Another studies have indicated that synovial sarcoma is classified as a cold tumor, with the behavior of malignant tumor cells being regulated by the SS18-SSX fusion protein." (PMID 39735532, 2024).